IL22 (interleukin 22)
Diseases named in the same sentence as IL22 in open-access papers (continued):
Sharing a sentence is not in itself a finding about the gene and the disease.
staphylococcus aureus infection (2 papers, 2022 to 2024). An infectious process in which the bacteria Staphylococcus aureus is present. "By inserting the IL-22 gene into the previously constructed mammary tissue-specific expression plasmid, the range of action of IL-22 was limited, drug safety was improved, and Staphylococcus aureus infection was significantly reduced in vivo and in vitro." (PMID 39453107, 2024).
tauopathy (2 papers, 2023 to 2026). Neurodegenerative disorders involving deposition of abnormal tau protein isoforms (tau proteins) in neurons and glial cells in the brain. "In this perspective article, we take a closer look at long COVID as a probable tauopathy, discussing potential biomarkers such as microbial cell-free DNA (mcfDNA), interleukin 22 (IL-22), and phosphorylated Tau (pTau)." (PMID 37628830, 2023). "While AMI treated P301S mice demonstrated significant decrease in the levels of MYD88, NF-KB, TNF-α and IL-22 by 52% (P < 0.0001, F = 770.9), 54% (P < 0.0001, F = 794.5), 49% (P < 0.0001, F = 385.6) and 39% (P < 0.0001, F = 668.8) respectively when compared to tauopathy model." (PMID 41484454, 2026).
thyroid cancer (2 papers, 2019 to 2020). "In thyroid cancer, IL-22 induces miR-595 expression, which in turn downregulates Sox17 expression, thereby enhancing the migration and invasion of thyroid cancer." (PMID 32655554, 2020). "To further elucidate their roles in thyroid cancer, we determined expression levels of IL-22, TRIM30 and β-catenin in 116 pairs of clinical PTC and 116 adjacent nontumorous tissues (ANT)." (PMID 31823782, 2019).
Trichuris trichiura infection (2 papers, 2019). "Trichuris trichiura infection has therapeutic effects on UC, and a recent study proved the involvement of IL-22 in this process." (PMID 31687015, 2019). "Although a role of IL-22 in inducing goblet cell hyperplasia and promoting microbiota homeostasis during whipworm infections cannot be excluded, the induction of this mechanism of worm expulsion in the T. muris model is strongly dependent on the actions of IL-13 and regulated by IL-10." (PMID 30640950, 2019).
tuberculoid leprosy (2 papers, 2013 to 2014). A principal or polar form of leprosy in which the skin lesions are few and are sharply demarcated. "Of the 24 soluble mediators of inflammation that were measured, 7 showed significant differences between lepromatous and tuberculoid leprosy (CCL2, CCL17, CCL18, IFNA1, IL10, IL22, and TNF)." (PMID 25412496, 2014).
vaginal infection (2 papers, 2019). "IL-17 and IL-22 both play a key role in protective immunity, resisting C. albicans invasions, including both oral infections and vaginal infections." (PMID 31333606, 2019). "Of note, the phenotype of Il18−/− mice strongly resembles that observed in Il22−/− mice, further pointing to the collaborative IL-18 and IL-22 cross-talk in protection against Candida vaginal infection." (PMID 31681274, 2019).
vasculitis (2 papers, 2015 to 2021). "A number of types of vasculitis have been identified, and several studies have focused on Th22/IL-22 in vasculitis." (PMID 34295334, 2021).
viral myocarditis (2 papers, 2012 to 2014). Myocarditis that is caused by an infection with a viral agent. "However, in IL-17A-deficient mice, IL-22 exacerbates CVB3-induced acute viral myocarditis." (PMID 25547181, 2014). "Treatment of AVMC mice with Anti-IL-22 Ab exacerbated the severity of viral myocarditis, verified by lower survival rate, higher HW/BW ratios and cardiac pathological scores." (PMID 23050732, 2012).
abdominal aortic aneurysm (1 paper, 2022). Enlargement and ballooning of the vessel that supplies arterial blood to the abdomen, pelvis and legs. "This study evaluated the effects of IL-22 on AD/abdominal aortic aneurysm (AAA) formation in angiotensin II (Ang II)-infused ApoE-/- mice." (PMID 35340206, 2022).
Acanthamoeba infection (1 paper, 2025). "Several cytokines, such as interferon-gamma (IFN-γ), interleukin (IL)-4, IL-10, IL-17A, IL-17F, and IL-22, are rapidly produced and secreted in response to Acanthamoeba infection." (PMID 40109888, 2025). "Several cytokines, for example, IFN-γ, IL-4, IL-10, IL-17A, IL-17F, and IL-22, were reported to rapidly produce and secrete in response to the Acanthamoeba infection but not IL-1β cytokine." (PMID 40109888, 2025).
adenovirus infection (1 paper, 2019). "IL-22 promotes TLO development in salivary glands in response to local adenovirus infection, and TLO formation in human rheumatoid synovitis is strongly associated with the upregulation of IL-23, IL-21, IL-22, and IL-17F." (PMID 31921189, 2019).
airway allergy (1 paper, 2023). "The findings reported in these studies show that the IL-22 function in the airway allergy remains to be elucidated given that the collecting findings are controversial." (PMID 37445595, 2023). "Studies show that the IL-22 function in airway allergy appears to be time-dependent, whereas IL-22 was protective during the allergen challenge and deleterious during the sensitization." (PMID 37445595, 2023).
ankylosis (1 paper, 2019). Fixation and immobility of a joint. "Further studies should be performed to assess the effects of IL-12, IL-22 and IL-23 signaling blockade for treatment of entheseal ossification and ankylosis with McH/lpr-RA1 mice." (PMID 31200688, 2019). "The blockade of IL-17 signaling was achieved in this study; however, this signal suppression might be insufficient, as other signaling pathways (such as IL-12, IL-22 and IL-23) could be involved in the mechanisms of entheseal ossification and ankylosis." (PMID 31200688, 2019).
Anorexia (1 paper, 2021). Lack of desire to eat (loss of appetite). "Within these pathways, many cell cytokines, including those associated with inflammation, such as IL-1, IL-6, TNF-10, IL-22, and TNF-alpha, contribute to the anorexia of cancer patients." (PMID 34724970, 2021).
anthrax (1 paper, 2015). "Thus, cutaneous anthrax induces a broad T cell memory response characterized not only by the presence of Th1 cytokines IFNγ and TNFα, but also Th2 (IL-5 and IL-13), Th17 (IL-17/IL-22), Th22 (IL-22) and Th9 (IL-9) cytokines and a potentially regulatory IL-10 response." (PMID 26075052, 2015).
Aortic dissection (1 paper, 2022). Aortic dissection refers to a tear in the intimal layer of the aorta causing a separation between the intima and the medial layers of the aorta. "A previous study reported that IL-22 levels were significantly increased in the aortas of patients with aortic dissection (AD) and reported a further increase in IL-22 expression and substantial immune cell infiltration in the torn sections." (PMID 35340206, 2022). "Our previous study showed that interleukin-22 (IL-22) levels were increased in patients with aortic dissection (AD)." (PMID 35340206, 2022).
arbovirus infection (1 paper, 2021). A viral infection that is transmitted by an arthropod. "Considering the BBB permeability is a crucial early event for neurological damage, the ratio of IL-22/IL-17A levels in serum seemed to be an accurate serological marker for neurological assessment risk in arbovirus infections." (PMID 33776990, 2021). "Soluble serum (IL-22, RANTES, Eotaxin) and CSF (IL-8, EGF, IL-3) mediators may discriminate putative risks for neurological complications following arbovirus infections." (PMID 33776990, 2021).
autoimmune pancreatitis (1 paper, 2024). "In experimental autoimmune pancreatitis, AHR activation augments IL22 production in pancreatic α cells, suppressing chronic fibrotic and inflammatory processes via IL22 production." (PMID 38612627, 2024).
autoimmune polyglandular syndrome type 1 (1 paper, 2020). "Furthermore, neutralizing autoantibodies to IL‐17A, IL‐17F, and IL‐22 are associated with an increased susceptibility to C. albicans infections in patients with autoimmune polyglandular syndrome type 1 (APS1) due to mutations in autoimmune regulator (AIRE)." (PMID 32609955, 2020).
benign breast tumours (1 paper, 2025). "An important discovery of our research is the statistically significant negative correlation between IL-21 and IL-22 concentrations in the blood serum of women with benign breast tumours." (PMID 40729006, 2025).
bladder infection (1 paper, 2022). "Our functional studies using the Rag2−/− ILC depletion model, together with the scRNAseq analysis following UPEC challenge, identified IL17 production as the major contribution of ILC3s in acute bladder infection, with a more limited contribution to IL22 production." (PMID 35845169, 2022). "Notably, IL22 and IL17 have also been detected in human urine in the context of candida UTI, supporting the conclusion that this axis may play a similarly important role in human bladder infection." (PMID 35845169, 2022).
bone metastasis (1 paper, 2024). Transfer of a neoplasm from its primary site to bones. "Patients with bone metastasis had higher serum IL-22 levels (p = 0.008), and patients with brain metastasis had lower IL-4 levels (p = 0.025)." (PMID 39502692, 2024).
Bovine mastitis (1 paper, 2024). INFLAMMATION of the UDDER in cows. "The application of the yak IL-22 gene in the treatment of bovine mastitis in actual production still needs to be further developed, and the improvement of the biological activity of the IL-22 protein in vivo in gene therapy to achieve better therapeutic effects also needs to be further studied." (PMID 39453107, 2024).
brain inflammation (1 paper, 2022). "Although IL-22 is involved in the development of inflammatory responses, there have been no reports of its role in brain inflammation." (PMID 35054942, 2022).
bronchiectasis (1 paper, 2025). Segmental, irreversible dilation of the bronchial tree resulting in the accumulation of secretions which leads to obstruction. "Finally, IL-22 was highest in the control group and lowest in the CF and bronchiectasis groups." (PMID 40876742, 2025).
cardiac arrest (1 paper, 2020). Cessation of breathing and/or cardiac function. "In this single-center, case-control study, we measured the plasma levels of IL-17, IL-22, IL-23 and IL-33 in 21 cardiac arrest patients with ROSC at three time-points (baseline [within 1 h post ROSC], 2 days post ROSC and 7 days post ROSC)." (PMID 32293300, 2020).
cerebral infarction (1 paper, 2021). An ischemic condition of the brain, producing a persistent focal neurological deficit in the area of distribution of the cerebral arteries. "After ischemia-reperfusion, significant cerebral infarction was observed in the MCAO group, but IL-22 treatment significantly decreased the infarct volume of mice." (PMID 33790691, 2021).
Cholestatic liver disease (1 paper, 2020). "The expression of hepatic IL-22 mRNA was higher in HCV hepatitis than that in cholestatic liver disease, although the serum IL-22 level was not significantly different between HCV hepatitis and the normal control group." (PMID 32760208, 2020).
chronic asthma (1 paper, 2019). An asthma that is characterized by the development of persistent airway inflammation and recurrent attacks of breathlessness and wheezing, which vary in severity and frequency. "Further support for the presence of a mixtured Th phenotype in pathological situations is provided by a study on patients with chronic asthma, where CD4+T-cell clones with a Th17/Th2 phenotype that also produced IL-22 were identified." (PMID 30893757, 2019).
chronic gastritis (1 paper, 2023). Inflammation of the stomach that is chronic in nature. "Besides, this study proved that IL22+ CD4+ T cells and Foxp3+ Treg cells were positively correlated with H. pylori colonization and the severity of chronic gastritis." (PMID 36705412, 2023).
chronic inflammatory demyelinating polyradiculoneuropathy (1 paper, 2013). A rare neurological disorder in which there is inflammation of nerve roots and peripheral nerves and destruction of the fatty protective covering (myelin sheath) over the nerves. "The frequency of Th17 cells in cerebrospinal fluid (CSF) and the level of IL-17 in plasma were detected significantly higher in active chronic inflammatory demyelinating polyradiculoneuropathy (CIDP) and furthermore, the levels of IL-17 and IL-22 in CSF were correlated with GBS severity." (PMID 24000328, 2013).
chronic lung infection (1 paper, 2020). "Th17 lineage cytokines (IL-17A, IL-17F, and IL-22) and chemokines (CXCL1, CXCL2, CXCL5, and CXCL8) are known to control chronic lung infection caused by mycobacteria." (PMID 33520738, 2020).
colonic disease (1 paper, 2024). "The IL-22, which is primarily produced by ILC3 and plays a protective role in the intestinal mucosal barrier, was further measured to further confirm the involvement of ILC3 in colonic disease development." (PMID 38343544, 2024).
conjunctivitis (1 paper, 2025). Inflammation of the conjunctiva of the eye. "Regarding Th17/Th22 responses, IL-17A and IL-22 mRNA expression levels increased in the right eye, which had more severe conjunctivitis, than in the left." (PMID 40861543, 2025). "In ophthalmology, we have previously reported that IL-22 levels increase in dupilumab-associated conjunctivitis (DAC) and that the levels of IL-22 mRNA expression are useful for diagnosing DAC in the ocular surface test." (PMID 40861543, 2025). "Both IL-22 and IL-17A may be involved in the pathophysiology, but the clinical findings and pathology of IL-22 and IL-17A-associated conjunctivitis have not been fully elucidated and require further research." (PMID 40861543, 2025).
coronary atherosclerosis (1 paper, 2014). Atherosclerosis of the coronary vasculature. "In fact, receptors for IL-22 are absent in immune cells but instead restricted to peripheral tissues, indicating the possibly direct roles of Th22 to coronary atherosclerosis." (PMID 24803740, 2014).
cutaneous melanoma (1 paper, 2020). A primary melanoma arising from atypical melanocytes in the skin. "Although the direct impact and molecular mechanisms of interleukin 22 on human malignancies had been extensively investigated in a great number of previous studies, few report aim at the direct role of interleukin 22 on cutaneous melanoma." (PMID 32201538, 2020).
cutaneous sarcoidosis (1 paper, 2020). "Here, we focused on cutaneous sarcoidosis and also report a significant increase in IL26 gene expression whereas the gene expressions of IL22 and IL17A were not affected." (PMID 33057074, 2020).
deep vein thrombosis (1 paper, 2024). "For patients with deep vein thrombosis, elevated IL-22 levels could be shown, which is interesting regarding PH group IV." (PMID 38612795, 2024).
delirium (1 paper, 2025). A disorder characterized by confusion; inattentiveness; disorientation; illusions; hallucinations; agitation; and in some instances autonomic nervous system overactivity. "We identified several soluble factors and immune cell types linked to delirium, including IL-1α, IL-22, IL-21, CCL11, CXCL1, CXCL13, and VEGF-A, as well as exhausted B cells and activated T cells." (PMID 41219650, 2025). "Overall, delirium was correlated with several cytokines (decreased IL-22, IL-21, IL-1α), chemokines (increased CXCL1, CCL11, CXCL13), and growth factors (increased HGF, and a tendency towards increased VEGF-A)." (PMID 41219650, 2025).
dermatophytosis (1 paper, 2021). A common fungal infection of the stratum corneum of the skin, hair, or nails by a dermatophyte. "The authors hypothesized that a low DEFB4 copy number was a risk factor for dermatophytosis, together with elevated IL-22 levels implicated in its pathogenesis." (PMID 33523393, 2021).
diabetic encephalopathy (1 paper, 2025). A brain disease that is characterized by functional impairment of cognition, cerebral signal conduction, neurotransmission and synaptic plasticity, and underlying structural pathology associated with diabetes. "Collectively, these findings indicate that Th22 cells promote changes in the reactivity of microglia by secreting IL-22 in DM model mice, which participates in and accelerates the progression of cognitive dysfunction in diabetic encephalopathy." (PMID 39630234, 2025).
diabetic neuropathy (1 paper, 2023). A chronic, pathological complication associated with diabetes mellitus, where nerve damages are incurred due to diabetic microvascular injury involving small blood vessels that supply these nerves, resulting in peripheral and/or autonomic nerve dysfunction. "In addition to controlling glycolipid metabolism and decreasing the buildup of inflammation and reactive oxygen species (ROS), a combination of a VEGF-B monoclonal antibody and interleukin-22 (IL-22) may protect against diabetic neuropathy." (PMID 37375796, 2023).
dissection (1 paper, 2020). The separation and isolation of tissues for surgical purposes, or for the analysis or study of their structures. "This limited evidence supports the role of IL-11, IL-22, IL-17, and IL-3 in aortic dissection; however, further investigations are needed to determine whether these interleukins have a role in the early stages of TAA development." (PMID 33081376, 2020).
drug-induced liver injury (1 paper, 2021). A spectrum of clinical liver diseases ranging from mild biochemical abnormalities to acute liver failure, caused by drugs, drug metabolites, and chemicals from the environment. "Patients with drug-induced liver injury (DILI) have increased intrahepatic and peripheral Th22 cells and IL-22 levels, and the liver IL-22 level is positively correlated with regeneration." (PMID 34295334, 2021).
ductal carcinomas (1 paper, 2024). "These S100 gene products have also been shown to be secreted due to IL-22 and IL-17 signaling, have been associated with poor outcomes in ductal carcinomas, and have been affected after AI treatment in an animal model." (PMID 39057065, 2024).
duodenitis (1 paper, 2025). Acute or chronic inflammation of the duodenum. "Taken together, these data indicate that A20ZF7 intestines respond aberrantly to “WT” microbiota by expressing markedly elevated expression of IL-22 that, in turn, perturbs IEC functions, disrupts intestinal epithelial barrier integrity, and causes duodenitis." (PMID 40892518, 2025). "Colonization of adult germ-free mice with microbiota from adult WT specific pathogen–free mice drives duodenal IL-22 expression and duodenitis." (PMID 40892518, 2025).
dyslipidaemia (1 paper, 2022). "Circulating IL-22+ ILC3s were increased in axSPa patients with dyslipidaemia compared to patients without dyslipidaemia or healthy controls." (PMID 35634348, 2022).
eating disorder (1 paper, 2021). A broad group of psychological disorders with abnormal eating behaviors leading to physiological effects from overeating or insufficient food intake. "However, eating disorder psychopathology was negatively associated with concentrations of IL-22, IL-27, MCP-1, MIP-1β and TNF-β, with a moderate effect size, and Eotaxin-3, with a large effect size." (PMID 34442458, 2021). "Overall, it is likely that extremes in BMI have a greater effect on many inflammatory markers (e.g., IL-7, IL-12/IL-23p40, IL-22) than comorbid psychiatric symptoms and/or eating disorder psychopathology." (PMID 34442458, 2021).
empyema (1 paper, 2021). An accumulation of pus in a body cavity, usually the pleural space. "The diagnostic accuracy of CD4+IL-9+, CD4+IL-17+, CD4+IL-22+, CD4+CD25+FOXP3+ T cells, and ADA in the differentiation of tuberculous from non-tuberculous effusions (malignant, empyema, and parapneumonic effusions)." (PMID 34925358, 2021).
Enterobacteriaceae Infections (1 paper, 2024). Infections with bacteria of the family ENTEROBACTERIACEAE. "Moreover, IL-22, derived from ILC3s, is crucial in regulating LCN2 production in human IECs, thereby facilitating host defense against Enterobacteriaceae infections." (PMID 39300068, 2024).